TCF12 (transcription factor 12)
Diseases named in the same sentence as TCF12 in open-access papers (continued):
Sharing a sentence is not in itself a finding about the gene and the disease.
craniosynostosis (continued). "The AD in both jaws was not statistically significantly different in the Saethre-Chotzen syndrome or the TCF12-related craniosynostosis than those of the control group (maxillary AD: β = − 0.80, 95% CI − 2.04, 0.44; mandibular AD: β = − 0.02, 95% CI − 1.17, 1.12, respectively)." (PMID 30392078, 2019). "However, the ratios seen in Saethre-Chotzen syndrome or TCF12-related craniosynostosis suggest that these patients have a more normal growth pattern compared to Muenke patients." (PMID 30392078, 2019). "In Apert and Crouzon patients, the smaller mandibular arch dimensions in Muenke and Saethre-Chotzen syndromes or TCF12-related craniosynostosis patients are probably the result of a lingual compensatory growth direction of mandibular teeth towards the narrow maxilla." (PMID 30392078, 2019). "Furthermore, a less restricted maxilla results in a more normal growth pattern that acknowledges the normal ratios in Saethre-Chotzen syndrome or TCF12-related craniosynostosis patients." (PMID 30392078, 2019). "This suggests that Saethre-Chotzen syndrome or TCF12-related craniosynostosis may share other craniofacial features, such as the size of the maxilla or the dental arch dimensions." (PMID 30392078, 2019). "The clinical implications for orthodontic treatment of patients with Muenke and Saethre-Chotzen syndromes or TCF12-related craniosynostosis lie in the high prevalence of smaller dental arch dimensions and posterior crossbites that should be seen in relation to craniosynostosis." (PMID 30392078, 2019). "It remains unclear whether the smaller dental arch dimensions in patients with Muenke and Saethre-Chotzen syndromes or TCF12-related craniosynostosis is the result of craniofacial surgery or if it is syndrome-related or both." (PMID 30392078, 2019). "The maxillary and mandibular ICW in the Saethre-Chotzen syndrome or the TCF12-related craniosynostosis were statistically significantly smaller than those of the control group (β = − 1.99, 95% CI − 3.37, − 0.60; β = − 2.24, 95% CI − 3.41, − 1.07, respectively)." (PMID 30392078, 2019). "The maxillary and mandibular AL in the Saethre-Chotzen syndrome or the TCF12-related craniosynostosis was statistically significantly smaller than those of the control group (β = − 28.66, 95% CI − 31.88, − 25.43; β = − 25.25, 95% CI − 28.35, − 22.15, respectively)." (PMID 30392078, 2019). "Furthermore, we suspect that we have not included all patients with Muenke and Saethre-Chotzen syndromes or TCF12-related craniosynostosis because of their inconspicuous phenotype." (PMID 30392078, 2019). "Further research is needed to determine whether a specific retention protocol is necessary in order to achieve the same results in stability after successful orthodontic treatment in patients with Muenke syndrome, Saethre-Chotzen syndrome, and TCF12-related craniosynostosis." (PMID 34904178, 2022). "We show that asymmetric distribution of Erg and Six2 is lost in Twist1+/−;Tcf12+/− mutants, and in a companion study that similar asymmetric distribution of Grem1+ progenitors is lost in Tcf12−/− mutants, consistent with bones meeting end-on-end and fusing in these craniosynostosis models." (PMID 34376651, 2021). "Furthermore, future studies should be conducted with a larger case group to increase generalizability by pooling of data and include more covariables to further explore the most often seen asymmetry in patients with Muenke and Saethre-Chotzen syndromes or TCF12-related craniosynostosis." (PMID 30392078, 2019). "As seen in Apert and Crouzon patients, the smaller maxillary transverse dimensions in Muenke and Saethre-Chotzen syndromes or TCF12-related craniosynostosis patients may be the result of maxillary constriction and the fusion of the maxillary surrounding sutures." (PMID 30392078, 2019).
craniosynostosis (continued). "On the other hand, it would be important to include other genes, such as TCF12 (OMIM 600,480), MSX2 (OMIM 123,101), RAB23 (OMIM 606,144), and EFNB1 (OMIM 300,035), to determine their participation in craniosynostosis in the Mexican population." (PMID 32510873, 2020). "The prevalence of TCF12-related craniosynostosis is not yet determined because this syndrome was recently discovered." (PMID 34904178, 2022). "This could suggest incomplete penetrance, which may be similar to other craniosynostosis syndromes such as TCF12 and SMAD 6-related craniosynostosis and could potentially complicate genetic counseling." (PMID 34900871, 2021). "This theory is supported by the ratios for the ICW, AD, and AL in Saethre-Chotzen syndrome or TCF12-related craniosynostosis patients, which are not statistically significantly different than those of the control group." (PMID 30392078, 2019). "It is unclear why the mandibular IMW and AD dimensions in Saethre-Chotzen syndrome or TCF12-related craniosynostosis patients were not statistically significantly different from those of the control group." (PMID 30392078, 2019). "To date, we have tested, by dideoxy‐sequencing of TCF12, 105 Dutch syndromic and nonsyndromic coronal craniosynostosis index patients with negative results for FGFR2, FGFR3, and TWIST1 testing." (PMID 27158814, 2016). "The index patient of family 3 does not exhibit the classical clinical phenotype of TCF12‐related craniosynostosis, since all vault sutures were fused except for the metopic suture." (PMID 27158814, 2016). "In the original report, no whole exon deletion of TCF12 was identified using MLPA analysis (n = 226), suggesting that TCF12 microdeletion is not a frequent cause of isolated craniosynostosis." (PMID 25871887, 2015). "Additionally, the AD in both jaws of patients with Saethre-Chotzen syndrome or TCF12-related craniosynostosis was not statistically significantly smaller compared to those of the control group." (PMID 30392078, 2019). "Therefore, it remains unclear whether or not midface hypoplasia is characteristic in Muenke syndrome, Saethre-Chotzen syndrome, and TCF12-related craniosynostosis and whether or not it is of clinical significance." (PMID 34904178, 2022).
breast carcinoma (16 papers, 2009 to 2024). "While GRHL2 motifs remain the most common, there is the appearance of motifs similar to those of FOX and Tcf12 transcription factors; transcription factors linked to initiation of EMT, endocrine therapy resistance, and invasion in breast cancer." (PMID 39199676, 2024). "miR-200 was found to inhibit CAF activation and ECM remodeling by targeting FLI1 and TCF12, thereby interfering with the invasion and metastasis of breast cancer cells." (PMID 38766528, 2024). "We observed that the top five strongest TF co-occupancy pairs associated with breast cancer risk were FOXA1 + E2F1, FOXA1 + NR2F2, FOXA1 + ESR1, FOXA1 + SIN3, and FOXA1 + TCF12." (PMID 34518541, 2021). "It was reported that TCF12 enhanced CXCL12 secretion in CAFs to promote the growth of breast cancer cells." (PMID 31534521, 2019). "In addition, a decreased miR-200s level induced expression of Fli-1 (friend leukemia integration 1) and TCF-12 (transcription factor 12), which are correlated with poor outcome in breast cancer patients." (PMID 26828520, 2016). "Notably, CAF TCF12 has been linked to promoting breast cancer growth, whereas elevated FOSL2 levels in breast CAFs are significantly associated with angiogenesis and clinical progression in breast cancer." (PMID 38445456, 2024). "For example, TGF-β secreted by breast cancer cells has been reported to induce a CAF phenotype in normal fibroblasts by down-regulating miR-200 and up-regulating transcription factor 12 (TCF12) and friend leukemia virus integration 1 (Fli-1) expression, thereby contributing to ECM remodeling." (PMID 32957712, 2020). "Similarly, the top hub TFs we found in the integrated network such as SP1, SP2, TCF12, MYC, JUN and EGR2, were also well-known regulators in breast cancer." (PMID 26763900, 2015).
glioma (15 papers, 2015 to 2026). A benign or malignant brain and spinal cord tumor that arises from glial cells (astrocytes, oligodendrocytes, ependymal cells). "As the target gene of miR-486-3p, the transcription factor TCF12 is significantly differentially expressed in various types of glioma and is associated with a poor prognosis." (PMID 38725030, 2024). "Immunofluorescence confirmed upregulated expression of MSTN and TCF12 in glioma tissues and their co-localization with macrophages." (PMID 41899441, 2026). "Comparative analysis demonstrated elevated LITAF, OSMR, and TCF12 expression in glioma versus normal tissues at transcriptional level." (PMID 40859405, 2025). "With respect to the molecular mechanism, we found that LINC00606 mainly exists in the cytoplasm and promotes glioma progression by sponging miR-486-3p, which targets TCF12." (PMID 38725030, 2024). "In conclusion, we demonstrated that DHX9 was elevated in gliomas and promoted the proliferation, migration, invasion of glioma cells, and the infiltration of TAMs by targeting the TCF12/CSF1 axis." (PMID 36377508, 2023). "The cell function assay showed that TCF12 silencing diminished the promotion effect on glioma proliferation, migration and invasion induced by DHX9." (PMID 36377508, 2023). "There is an article confirms that DHX9 can increase TAM infiltration in glioma by regulating the TCF12/CSF1 axis, and then promote its polarization into M2 Macrophage, which finally promote the progression of GBM." (PMID 37602882, 2023). "DHX9 silencing decreased the expression of colony‐stimulating factor 1 (CSF1), which partially restored the inhibitory effect on malignant progress of glioma and infiltration of TAMs caused by DHX9 knockdown by targeting the transcription factor 12 (TCF12)." (PMID 36377508, 2023). "Circ-PIP5K1A is a possible prognostic marker for glioma and affects glioma evolution via the miR-515-5p-mediated TCF12/PI3K/AKT axis." (PMID 35883576, 2022). "Overall, the study illustrated that CircPIP5K1A is a potential prognostic marker in glioma and regulates glioma evolvement by modulating the miR-515-5p-mediated TCF12/PI3K/AKT axis." (PMID 33413401, 2021). "We conducted western blot to explore the expression characteristics of TCF12 in tumors and found that TCF12 was upregulated in glioma tissues (compared with that in adjacent normal tissues." (PMID 33413401, 2021). "We conducted a gain- and loss-of functions assay of TCF12 in U87 and A172 respectively to verify the influence of TCF12 on glioma (P < 0.05)." (PMID 33413401, 2021). "It was found that glioma patients with higher level of TCCF12 had poorer survival than those with lower level of TCF12 (P > 0.05)." (PMID 33413401, 2021). "In summary, this study aims to research the function of a novel circPIP5K1A/miR-515-5p/TCF12/PI3K/AKT axis in glioma, improve the study of its molecular mechanism, and provide referential molecular markers for clinical diagnosis and treatment for glioma." (PMID 33413401, 2021). "In addition, the target gene TCF12 is highly expressed in glioma and acts as a transcription factor to control the transcription of LINC00606, PTEN, and KLLN." (PMID 38725030, 2024). "Furthermore, TCF12 knockdown eliminated the carcinogenic effect caused by DHX9 overexpression, suggesting that DHX9 promoted the CSF1‐induced glioma growth and recruitment of TAMs in a TCF12‐dependent manner." (PMID 36377508, 2023). "The mechanistic investigations showed that DHX9 promote glioma progress by targeting the TCF12/CSF1 axis, indicating that DHX9 might be a novel target for precise immunotherapies against gliomas." (PMID 36377508, 2023). "Consistent with previous findings, we found that TCF12 silence could inhibit the malignant phenotype of gliomas." (PMID 36377508, 2023).
glioma (continued). "DHX9/TCF12/CSF1 axis regulated the increases in the infiltration of TAMs to promote glioma progression and might be a novel potential target for future immune therapies against gliomas." (PMID 36377508, 2023). "Functionally, it could promote the progression of glioma by elevating the expression level of transcription factor 12 (TCF12) by sponging miR-515-5p, thereby activating the PI3K/AKT pathway." (PMID 36142352, 2022). "We then analyzed the relationship between TCF12 expression with glioma prognosis." (PMID 33413401, 2021). "Furthermore, the Transwell assay was employed to investigate the TCF12 regulation on E-cadherin, Vimentin and N-cadherin in glioma cells." (PMID 33413401, 2021). "Interestingly, there was a positive relationship between circPIP5K1A and TCF12 in glioma tissues (R2 = 0.499, P < 0.0001)." (PMID 33413401, 2021). "In addition, Person correlation analysis revealed that circPIP5K1A and miR-515-5p was negatively correlated in glioma cells (R2 = 0.571, P < 0.001), which was the same of TCF12 and miR-515-5p (R2 = 0.463, P < 0.001)." (PMID 33413401, 2021). "The rescue experiment was conducted to verify whether there was a regulatory axis of circPIP5K1A/miR-515-5p/TCF12/PI3K/Akt in glioma." (PMID 33413401, 2021). "Irrespective of the downstream effects of TCF12 mutation on glioma, our data are compatible with TCF12 having haploinsufficient tumour suppressor function." (PMID 26068201, 2015). "However, whether circPIP5K1A and TCF12 affect glioma by regulating the PI3K/AKT pathway remains elusive." (PMID 33413401, 2021). "The expression of LINC00606 and ATP11B in glioma and normal brain tissues was evaluated by qPCR, and the biological functions of the LINC00606/miR-486-3p/TCF12/ATP11B axis in GBM were verified through a series of in vitro and in vivo experiments." (PMID 38725030, 2024). "Here, we have confirmed through in vitro experiments that overexpressing TCF12 promotes cell proliferation, invasion and EMT, weakens apoptosis, and activates the PI3K/AKT signaling pathway in glioma." (PMID 33413401, 2021). "Of these TFGs, the role of TCF12, RUNX1T1, and LMNA in gliomas is still unclear and needs further investigation." (PMID 32695826, 2020). "In addition, we detected the expression level of TCF12 in HEB, U251, and U118 cells, the expression level of TCF12 is significantly increased in glioma cell lines." (PMID 38725030, 2024). "Then, the expression of CSF1 in these cells was assessed by qRT‐PCR, which showed that the DHX9‐overexpression plasmid failed to upregulate CSF1 in si‐TCF12‐transfected glioma cells." (PMID 36377508, 2023). "DHX9/TCF12/CSF1 axis regulate the infiltration of TAMs to promote glioma progression and may be a novel potential target for future immune therapies against gliomas." (PMID 36377508, 2023). "CEBPB might act in glioma by regulating CCL2, CCND1, THBS1, THBS2, SMAD5, SMAD6, TGFBR2, and TCF12." (PMID 27716259, 2016). "Additionally, CEBPB and TCF12 might function in glioma through targeting others (CEBPB → TCF12, CEBPB → TGFBR2, and TCF12 → TGFBR2)." (PMID 27716259, 2016).
colorectal cancer (10 papers, 2011 to 2024). A primary or metastatic malignant neoplasm that affects the colon or rectum. "TCF12 overexpression has been detected in many malignancies such as colorectal cancer, breast cancer, gallbladder cancer, hepatocellular carcinoma, melanoma, and pancreatic cancer." (PMID 39768127, 2024). "A correlation of TCF12 overexpression with colorectal cancer metastasis has also been suggested and validated." (PMID 25648588, 2014). "Chen and colleagues recently showed that extracellular Hsp90α could induce FN expression by activating cellular signalling pathways in transcription factor 12 (TCF-12) overexpressing colorectal cancer cell lines." (PMID 24466266, 2014). "Furthermore, the level of nuclear TCF12 had a significant correlation to progression free survival in a cohort of 248 stage II colorectal cancer samples." (PMID 21999571, 2011). "In colorectal cancer cells, HSP90 with LRP1 triggers the expression of Transcription factor 12 (TCF12), increasing fibronectin and decreasing E-cadherin." (PMID 39363892, 2024). "TCF12 was observed to be co-expressed and co-immunoprecipitated with Bmi1 and EZH2 in human colorectal cancer (CRC) cells." (PMID 29435158, 2018). "However, whether or not TCF12 plays a role in cancer development and progression has not been determined yet except for the contradictory evidence in colorectal cancer." (PMID 26524630, 2015).
Saethre-Chotzen syndrome (10 papers, 2018 to 2024). Saethre-Chotzen syndrome (SCS) is an inherited craniosynostosis syndrome characterized by unilateral or bilateral coronal synostosis, facial asymmetry, ptosis, strabismus and small ears with prominent crus, among other less common manifestations. "Expression of the zebrafish homologs of the genes mutated in Saethre-Chotzen syndrome, twist1b and tcf12, is enriched in the MSM population." (PMID 39138165, 2024). "In Saethre-Chotzen syndrome, mutations in transcription factor 12 (TCF12) or twist-related protein 1 (TWIST1) genes ablate the coronal suture, as observed in human and rodent studies." (PMID 31828085, 2019). "Discovery of a selective requirement for tcf12 and twist1b in coronal suture formation in zebrafish has allowed us to gain a better understanding of the developmental basis of suture loss in Saethre-Chotzen syndrome." (PMID 30375332, 2018). "In Saethre-Chotzen syndrome, mutations in TCF12 or TWIST1 ablate a specific suture, the coronal." (PMID 30375332, 2018). "Heterozygous mutation of transcription factor 12 (TCF12), like that of TWIST1, can lead to the development of Saethre-Chotzen syndrome." (PMID 35451466, 2022). "Correspondingly, in Twist1+/−; Tcf12+/− mutants, a robust model for Saethre-Chotzen Syndrome coronal synostosis, Erg+/Six2+ progenitors were reduced as early as E14.5 yet ectocranial populations were relatively unaffected." (PMID 34376651, 2021). "Lineage tracing reveals an embryonic Six2+ osteoprogenitor population that contributes to the postnatal suture mesenchyme, with these progenitors being preferentially affected in a Twist1+/−; Tcf12+/− mouse model of Saethre-Chotzen Syndrome." (PMID 34376651, 2021). "The most common form of syndromic coronal synostosis is Saethre-Chotzen syndrome, which is caused by heterozygous loss-of-function mutations in TWIST1 or TCF12." (PMID 31869306, 2019).